GPBP1L1 (GC-rich promoter binding protein 1 like 1)
Description:
Possible transcription factor.
Synonyms: SP192
Tractability: Antibody: the Human Protein Atlas places it where antibodies can reach.
Gene: Protein-coding gene on chromosome 1 (45,627,284 to 45,688,408, reverse strand). Ensembl gene ENSG00000159592.
Subcellular location: Nucleus
Subcellular location (Human Protein Atlas): Nucleoplasm; Cytosol; Focal adhesion sites; Plasma membrane
Gene Ontology:
Molecular function: protein binding; DNA-binding transcription factor activity; DNA binding; RNA binding
Biological process: regulation of DNA-templated transcription; DNA-templated transcription; positive regulation of DNA-templated transcription
Cellular component: nucleus
Genetic constraint (gnomAD): Loss-of-function variants: 19 observed, 45.02 expected, observed/expected ratio (o/e) 0.42, 90% interval 0.29 to 0.62. The upper end of that interval is the gene's LOEUF score, 0.62, which puts it in group 2 of 6, group 1 being the genes least tolerant of losing a copy. Missense variants: 572 observed, 583.42 expected, observed/expected ratio (o/e) 0.98, 90% interval 0.92 to 1.05. Synonymous variants: 234 observed, 206.47 expected, observed/expected ratio (o/e) 1.13, 90% interval 1.02 to 1.26.
Homologues: Orthologues: chimpanzee GPBP1L1 (99% identical), dog GPBP1L1 (95% identical), guinea pig GPBP1L1 (94% identical), pig GPBP1L1 (93% identical), rat Gpbp1l1 (89% identical), mouse Gpbp1l1 (89% identical), rat Gpbp1l2 (89% identical), rat LOC100361636 (89% identical), rabbit GPBP1L1 (89% identical), tropical clawed frog gpbp1l1 (63% identical), zebrafish gpbp1l1 (61% identical). Paralogues in human: GPBP1 (43% identical).
Diseases named in the same sentence as GPBP1L1 in open-access papers:
GPBP1L1 is named in the same sentence as 6 diseases in open-access papers, as found by Europe PMC text mining. Sharing a sentence is not in itself a finding about the gene and the disease. The quoted sentences say what the papers report.
breast carcinoma (2 papers, 2016 to 2023). "Furthermore, as evident from S7B–S7D Table, several late-type genes showed a significant, but opposite, association with prognosis in one or more cohorts compared to the initial analysis of breast cancer, exemplified by RPL10, EIF4B, GPBP1L1 in NSCLC and RPL3, RPS6 and STEAP1 in ovarian cancer." (PMID 27926932, 2016).
astrocytoma (1 paper, 2024). "Moreover, the gene GPBP1L1 has a great impact in both LGG and GBM patient survival and showed distinct downregulation in oligodendroglioma when compared to both astrocytoma and GBM, but its role in cancer is still not described." (PMID 38812741, 2024).
glioma (1 paper, 2024). A benign or malignant brain and spinal cord tumor that arises from glial cells (astrocytes, oligodendrocytes, ependymal cells). "Furthermore, we could identify several novel glioma biomarkers likely helpful in both diagnosis and prognosis of the patients, including the genes PPP1R8, GPBP1L1, KIAA1614, C14orf23, CCDC77, BVES, EXD3, CD300A, and HEPN1." (PMID 38812741, 2024).
oligodendroglioma (1 paper, 2024). A well-differentiated (WHO grade II), diffusely infiltrating neuroglial tumor, typically located in the cerebral hemispheres. "Both these blocks are negatively correlated with the group of genes GPBP1L1, LRRC41, CSDE1, FBXO42, and SFRS4, which are associated with the oligodendroglioma type." (PMID 38812741, 2024).
cancer (1 paper, 2024). A tumor composed of atypical neoplastic, often pleomorphic cells that invade other tissues. "It is also interesting to note that the gene GPBP1L1 that was selected in both analyses (2 and 3 views) was never reported in any cancer study." (PMID 38812741, 2024).
GPBP1L1 also shares sentences with these, for which no sentence is quoted: ovarian carcinoma (1 paper).